RNF26 (ring finger protein 26)
Diseases named in the same sentence as RNF26 in open-access papers:
RNF26 is named in the same sentence as 18 diseases in open-access papers, as found by Europe PMC text mining. Sharing a sentence is not in itself a finding about the gene and the disease. The quoted sentences say what the papers report.
bladder cancer (5 papers, 2021 to 2025). "Since we identified that RNF26 was aberrantly overexpressed in bladder cancer cell lines and patient tissues, we sought to explore the underlying regulatory mechanism of RNF26." (PMID 34650035, 2021). "Then, the Gene Expression Profiling Interactive Analysis (GEPIA) web tool indicated that high expression of RNF26 was associated with shorter disease-free survival and OS times in bladder cancer." (PMID 34650035, 2021). "In this study, we applied bioinformatics analysis to identify RNF26 as a risk factor for bladder cancer." (PMID 34650035, 2021). "Collectively, we employed bioinformatics analysis, which showed that RNF26 is abnormally upregulated in bladder cancer cell lines and tissues and associated with a poor prognosis in bladder cancer." (PMID 34650035, 2021). "Here, bioinformatics analysis demonstrated that RNF26 was one of the risk factors for bladder cancer." (PMID 34650035, 2021). "We showed that the cell cycle signaling pathway had the most positive association with RNF26 in bladder cancer cells." (PMID 34650035, 2021). "The RNF26/TRIM21 complex is implicated in the proliferation and migration of bladder cancer cells via ZHX3." (PMID 40771930, 2025). "RNF26 can interact with p57, reducing its stability and enhancing the invasiveness of bladder cancer cells." (PMID 38890443, 2024). "Our previous studies indicated that RNF26 is upregulated in bladder cancer, leading to tumor growth by inducing p57 instability." (PMID 38890443, 2024). "In contrast, ectopic overexpression of FOXM1 enhanced FOXM1 binding to the promoter of RNF26 and increased the RNF26 expression level in bladder cancer cells." (PMID 34650035, 2021). "Collectively, we uncovered a novel FOXM1/RNF26/p57 axis that modulates the cell cycle process and enhances the progression of bladder cancer." (PMID 34650035, 2021). "Together, these data suggest that RNF26 acts as an E3 ligase to degrade p57 in bladder cancer cells." (PMID 34650035, 2021). "Consistently, we found that FOXM1 was positively correlated with RNF26 in multiple types of malignant tumors, including bladder cancer, colon cancer, cervical cancer, breast cancer, prostate cancer, pancreatic cancer, liver cancer, and gastric cancer." (PMID 34650035, 2021). "Then, we showed that RNF26 is abnormally upregulated in bladder cancer cells and tissues and that higher RNF26 expression is an unfavorable prognostic factor for bladder cancer." (PMID 34650035, 2021). "We established bladder cancer cells with knockdown of RNF26 or p57 alone or with simultaneous knockdown of RNF26 and p57." (PMID 34650035, 2021). "Together, our results suggest that RNF26 is abnormally overexpressed in bladder cancer and correlated with a poor prognosis in bladder cancer patients." (PMID 34650035, 2021). "Consistently, we showed that the expression levels of RNF26 were higher in bladder cancer cell lines than in immortalized human bladder epithelial cells (SV-HUC-1)." (PMID 34650035, 2021). "Then, we demonstrated that RNF26 overexpression was not only an unfavorable prognostic factor but also promoted cell growth and invasion in bladder cancer." (PMID 34650035, 2021). "Taken together, our results showed that RNF26 plays an important role in modulating the cell cycle process and interacts with p57 in bladder cancer cells." (PMID 34650035, 2021). "We further showed that RNF26 degrades p57 to promote cell cycle transition and bladder cancer cell proliferation." (PMID 34650035, 2021). "To further study the relationship between RNF26 and p57 in bladder cancer, we performed IHC analysis by staining RNF26 and p57 in a tissue microarray derived from a cohort of patients with bladder cancer." (PMID 34650035, 2021). "Since the clinicopathological features related to RNF26 expression indicated RNF26 as an oncogenic protein in bladder cancer, we investigated the biological effect of RNF26 in bladder cancer cells." (PMID 34650035, 2021).
bladder cancer (continued). "The CCK-8 assay, colony formation assay, and Transwell assay indicated that RNF26 silencing blocked bladder cancer cell growth and invasion." (PMID 34650035, 2021). "In contrast, overexpression of RNF26 enhanced the growth and invasion ability of bladder cancer cells." (PMID 34650035, 2021). "Furthermore, RNF26 has been shown to interact with another E3 ligase, TRIM21, enhancing its K48-linked ubiquitination in bladder cancer cells." (PMID 40771930, 2025). "Finally, RNF26 was identified as the only non-SCF complex ubiquitin ligase degrading p57KIP2 in response to FoxM1-stimulated RNF26 transcription which is one of the tumor promoting factors in development of bladder carcinoma." (PMID 38561743, 2024). "Additionally, it has been reported that abnormal overexpression of FOXM1 leads to upregulation of RNF26 in bladder cancer cells through the MuvB complex." (PMID 38890443, 2024). "The FOXM1/RNF26/p57 axis has been proposed as a new therapeutic target for bladder cancer." (PMID 38890443, 2024). "Moreover, we analyzed the protein and mRNA levels of RNF26 in samples derived from patients with bladder cancer." (PMID 34650035, 2021). "In addition, we demonstrated that aberrant overexpression of FOXM1 is responsible for the upregulation of RNF26 in bladder cancer cells through the MuvB complex." (PMID 34650035, 2021). "Moreover, we found that RNF26 interacts with p57 and decreases the stability of p57 to enhance the aggressiveness of bladder cancer cells." (PMID 34650035, 2021). "Furthermore, we treated bladder cancer cells with a FOXM1-specific inhibitor (FDI-6) to detect changes in RNF26 in T24 cells." (PMID 34650035, 2021). "Therefore, the specific role of RNF26 in cancers, especially bladder cancer, needs to be further studied." (PMID 34650035, 2021). "In this study, we used LASSO regression analysis to identify that RNF26 might be an E3 ligase that is crucial for the progression of bladder cancer." (PMID 34650035, 2021). "Then, we showed that RNF26 promotes the progression of bladder cancer in vitro and in vivo." (PMID 34650035, 2021). "Finally, we identified a novel FOXM1/RNF26/p57 signaling axis that modulates the cell cycle process and enhances the progression of bladder cancer." (PMID 34650035, 2021). "We also found that RNF26 was upregulated in bladder cancer tissues compared with adjacent tissues." (PMID 34650035, 2021). "Therefore, our data indicate that RNF26 is responsible for the progression of bladder cancer in vitro and in vivo." (PMID 34650035, 2021). "Here, we demonstrated that RNF26 enhances the proliferation and invasion of bladder cancer cells." (PMID 34650035, 2021). "Therefore, our results indicate that p57 is the downstream effector of RNF26 for modulating the proliferation of bladder cancer cells." (PMID 34650035, 2021). "We showed that RNF26 could bind with and degrade p57 in bladder cancer cells." (PMID 34650035, 2021). "Then, we aimed to explore whether RNF26 promotes bladder cancer cell proliferation via p57." (PMID 34650035, 2021). "Thus, the FOXM1/RNF26/p57 signaling axis could be a candidate target for the treatment of bladder cancer." (PMID 34650035, 2021). "Moreover, we found that RNF26 promotes bladder cancer progression." (PMID 34650035, 2021). "Therefore, our data suggest that FOXM1 regulates the expression of RNF26 in bladder cancer." (PMID 34650035, 2021). "However, the biological effect of RNF26 in cancer, especially in bladder cancer, is still elusive." (PMID 34650035, 2021). "Further experiments suggested that CDKN1C might interact with RNF26 in bladder cancer cells." (PMID 34650035, 2021). "Thus, we were curious about whether FOXM1 is responsible for the transcriptional regulation of RNF26 in bladder cancer." (PMID 34650035, 2021). "Therefore, we uncovered a novel FOXM1/RNF26/p57 axis in bladder cancer, which could be a candidate target for bladder cancer therapy." (PMID 34650035, 2021).
bladder cancer (continued). "To explore the underlying mechanism of how RNF26 enhanced the progression of bladder cancer cells, we performed gene set enrichment analysis (GSEA) of the TCGA-BLCA dataset to study the pathways in which RNF26 is involved." (PMID 34650035, 2021). "Then, we performed IHC staining to detect the protein level of RNF26 in bladder cancer tissues and nontumor bladder tissues in a tissue microarray for a cohort of patients with bladder cancer." (PMID 34650035, 2021). "The results showed that there was a negative correlation between RNF26 and p57 levels in the tissues of patients with bladder cancer, although the correlation is not so appreciable (Spearman r = −0.2701, P = 0.0154)." (PMID 34650035, 2021). "Furthermore, we also showed that RNF26 expression was upregulated in the bladder cancer tissues compared to nontumor bladder tissues." (PMID 34650035, 2021). "The cancer-related role of RNF26 in bladder cancer has never been mentioned." (PMID 34650035, 2021).
viral infection (4 papers, 2014 to 2024). "In the present study, we identified an E3 ubiquitin ligase, RING finger protein 26 (RNF26) that targeted MITA for K11-linked polyubiquitination upon viral infection." (PMID 25254379, 2014). "Viral infection potentiated this association and induced RNF26 to form punctate dots with MITA." (PMID 25254379, 2014). "As a result, knockdown of RNF26 promoted degradation of MITA after viral infection and prevented degradation of IRF3." (PMID 25254379, 2014). "Consistently, degradation of MITA was accelerated in RNF26 knockdown cells compared to control cells after viral infection." (PMID 25254379, 2014). "Unexpected, although knockdown of RNF26 inhibited virus-triggered induction of type I IFNs at the early phase of viral infection, it had opposite effect at the late phase of viral infection." (PMID 25254379, 2014). "RNF26 mediated K11-linked polyubiquitination of MITA and modulated expression of type I IFN triggered by viral infection." (PMID 25254379, 2014). "Furthermore, RNF26 promotes the K11-linked polyubiquitination of STING and increases the stability of STING following viral infection." (PMID 38429625, 2024). "Further experiments indicated that RNF26 protected MITA from RNF5-mediated K48-linked polyubiquitination and degradation that was required for quick and efficient type I IFN and proinflammatory cytokine induction after viral infection." (PMID 25254379, 2014). "Interestingly, SeV- or HSV-1-induced expression of the proinflammatory cytokines TNFα and IL-6 was inhibited by RNF26 knockdown at all examined time points after viral infection." (PMID 25254379, 2014). "In similar experiments, K11-linked polyubiquitination of VISA after viral infection was not affected by RNF26 knockdown." (PMID 25254379, 2014). "Knockdown of RNF26 potentiated K48- but not K63-linked polyubiquitination of MITA after viral infection." (PMID 25254379, 2014). "Since RNF26-mediated K11-linked polyubiquitination of MITA protected its degradation after viral infection, whether RNF26 regulates virus-triggered induction of type I IFNs was determined." (PMID 25254379, 2014). "Consistently, knockdown of RNF26 inhibited the expression of IFNB1 gene in various cells at the early phase and promoted it at the late phase of viral infection, respectively." (PMID 25254379, 2014). "Their findings indicated the temporal regulation of RNF26 on IFN-I production via distinct mechanisms, by which RNF26 exhibits a positive regulator in IFN-I responses in the early phase of viral infection while displaying as a negative modulator at the late stage." (PMID 36042206, 2022).
acute promyelocytic leukemia (2 papers, 2021 to 2024). An aggressive form of acute myeloid leukemia (AML), characterized by arrest of leukocyte differentiation at the promyelocyte stage, due to a specific chromosomal translocation t(15;17) in myeloid cells. "Previous studies have shown that RNF26 is upregulated in HL-60 (acute promyelocytic leukemia), HeLa S3 (cervical cancer), SW480 (colorectal cancer), and MKN7 (gastric cancer) cells." (PMID 38890443, 2024).
gastric cancer (2 papers, 2021 to 2024). A primary or metastatic malignant neoplasm involving the stomach. "RNF26 is upregulated ubiquitously in several human cancer cell lines, such as HL-60, HeLa S3, and MKN7, and gastric cancer tissues compared to normal controls." (PMID 34650035, 2021).
prostate carcinoma (2 papers, 2021 to 2024). A carcinoma that arises from epithelial cells of the prostate gland. "An additional study reported that UBTD1 can interact with another E3 ligase, RNF26, to upregulate the ubiquitination of autophagy-related protein p62 and enhance the lysosomal degradation of EGFR in prostate cancer cells." (PMID 39003255, 2024).
renal carcinoma (2 papers, 2022 to 2024). A carcinoma arising from the epithelium of the renal parenchyma or the renal pelvis. "Protein-protein interaction (PPI) network analysis indicated that the E3 ligase RNF26 was closely associated with CBX7 in renal cancer." (PMID 35342353, 2022). "We believe that the biological role of RNF26 in renal cancer remains incompletely understood and warrants further investigation." (PMID 38890443, 2024). "We further evaluated the relationship between RNF26 and CBX7 in renal cancer cells after knocking down RNF26." (PMID 35342353, 2022). "Here, we demonstrated that CBX7 was another substrate of RNF26 for degradation in renal cancer cells." (PMID 35342353, 2022). "Transwell assays, tube formation assays, CCK-8 assays, colony formation assays and xenograft assays were performed to examine the biological role of RNF26 in renal cancer cells.TCGA-KIRC dataset analysis and RT‒qPCR analysis were used to examine the pathways affected by RNF26 silencing." (PMID 38890443, 2024). "In addition, we also showed that combined knockdown of CBX7 and RNF26 attenuated the tumor growth inhibition effect induced by knockdown of RNF26 alone in renal cancer cells and a subcutaneous xenograft model." (PMID 35342353, 2022). "And RNF26 degraded CBX7 to promote the renal cancer cells proliferation." (PMID 35342353, 2022). "In contrast, overexpression of RNF26 promoted renal cancer cell growth." (PMID 35342353, 2022). "We demonstrated that RNF26 interacted with CBX7 and promoted CBX7 degradation in renal cancer cells, which provides novel insight into the low expression of CBX7 in cancers." (PMID 35342353, 2022). "Additionally, in ccRCC, we confirmed that RNF26 mediates the degradation of CBX7, thereby promoting the proliferation of renal cancer cells." (PMID 38890443, 2024). "Additionally, RNF26 interacts with TSC1 and regulates the proliferation, migration, and angiogenesis of renal cancer cells through the mTOR signaling pathway." (PMID 38890443, 2024). "Moreover, IHC staining of a renal cancer tissue microarray with anti-CBX7 and anti-RNF26 antibodies demonstrated that CBX7 expression was negatively correlated with RNF26 expression in the patient specimens (Spearman correlation r = -0.349, P = 0.0318)." (PMID 35342353, 2022). "To further explore the relationship between RNF26 and CBX7 in renal cancer cells, we treated renal cancer cells with or without a 26S proteasome inhibitor (MG132) under conditions of knockdown or overexpression of RNF26." (PMID 35342353, 2022). "It was not surprising that knockdown of RNF26 decreased the proliferation ability of renal cancer cells." (PMID 35342353, 2022). "Moreover, we found that RNF26 functioned as an E3 ligase for CBX7 and promoted CBX7 degradation in renal cancer cells." (PMID 35342353, 2022).
melanoma (1 paper, 2016). A malignant, usually aggressive tumor composed of atypical, neoplastic melanocytes. "Given that TOLLIP, EPS15, and TAX1BP1 were isolated from a human melanoma cell line using a proteomic approach, it stands to reason that other vesicle-associated adaptor proteins expressed in other cell types could exhibit a similar relationship with RNF26." (PMID 27368102, 2016).
renal cell carcinoma (1 paper, 2023). "The RNF26/CBX7 axis modulated the TNF pathway to promote Renal cell carcinoma proliferation." (PMID 37188171, 2023).
urinary system tumors (1 paper, 2024). "In urinary system tumors, recent reports have revealed the RNF26/CBX7 axis, where RNF26 promotes the degradation of CBX7, regulating the TNF signaling pathway in ccRCC and promoting ccRCC tumor growth." (PMID 38890443, 2024).
tumor (4 papers, 2021 to 2024). "Transwell, CCK-8 and tube formation assays demonstrated that depletion of TSC1 attenuated the effect of RNF26 overexpression on increasing tumor cell migration, proliferation, and angiogenesis." (PMID 38890443, 2024). "We showed that co-knockdown of RNF26 and p57 attenuated the tumor growth inhibition effect of RNF26 knockdown in vivo and in vitro." (PMID 34650035, 2021). "Then, we revealed that inactivation of the mTOR signaling pathway by everolimus not only attenuated the cell migration, proliferation and angiogenesis mediated by depletion of RNF26 in ccRCC cells but also abolished the ability of RNF26 to enhance tumor growth in vivo." (PMID 38890443, 2024). "The nude mouse study also revealed that inhibition of RNF26 reduced tumor growth in vivo." (PMID 38890443, 2024). "In addition, a nude mouse model demonstrated that the tumor-promoting effect of RNF26 could be diminished by knockdown of TSC1." (PMID 38890443, 2024). "However, rescue of RNF26 expression resulted in increased tumor growth." (PMID 34650035, 2021). "RNF26 promoted the degradation of CBX7 and enhanced ccRCC tumor growth." (PMID 35342353, 2022).
cancer (3 papers, 2021 to 2024). A tumor composed of atypical neoplastic, often pleomorphic cells that invade other tissues. "We believed that more substrates of RNF26 will be identified in the further to explain the role of RNF26 in malignant tumor." (PMID 35342353, 2022). "Since the mTOR signaling pathway is reported to regulate VEGFA expression and promote ccRCC angiogenesis and progression, we tested whether the mTOR signaling pathway is one of the key pathways mediating the cancer-related function of RNF26." (PMID 38890443, 2024). "In addition, the correlation between FOXM1 and RNF26 in the cancer patient samples was analyzed through the GEPIA web tool." (PMID 34650035, 2021). "Thus, we performed reciprocal IP to determine which protein truly bound to RNF26 in cancer cells." (PMID 34650035, 2021). "Notably, compared with overexpression of RNF26 alone, overexpression of RNF26 in CBX7 knockdown cells did not further increase cancer cell growth." (PMID 35342353, 2022).
infection (2 papers, 2014 to 2021). The state of being infected such as from the introduction of a foreign agent such as serum, vaccine, antigenic substance or organism. "At the early phase of infection, RNF26 mediates K11-linked polyubiquitination of MITA, which protects it from K48-linked polyubiquitination and degradation to facilitate the fast induction of type I IFN genes." (PMID 25254379, 2014). "Consistently, we performed cell cycle analysis, which demonstrated that knockdown of RNF26 blocked G1/S phase progression and that rescuing RNF26 expression by Tsin-RNF26 infection reversed this effect." (PMID 34650035, 2021). "Moreover, we also showed that recurring the expression of RNF26 after knockdown of RNF26 by infection with an shRNA-resistant Tsin-RNF26 construct reversed the growth-decreasing effect induced by RNF26 knockdown." (PMID 34650035, 2021).
RNF26 also shares sentences with these, for which no sentence is quoted: cervical cancer (2 papers); breast carcinoma (1); colon cancer (1); colorectal cancer (1); liver cancer (1); pancreatic cancer (1).